RN7SL663P (RNA, 7SL, cytoplasmic 663, pseudogene)
Gene: Miscellaneous RNA gene on chromosome 19 (38,200,234 to 38,200,532, forward strand). Ensembl gene ENSG00000275132.
Homologues: Orthologues: chimpanzee Metazoa_SRP (99% identical), macaque Metazoa_SRP (93% identical). Paralogues in human: RN7SL1 (82% identical), RN7SL2 (82% identical), RN7SL3 (81% identical), RN7SL697P (81% identical), RN7SL126P (80% identical), RN7SL650P (80% identical), RN7SL597P (79% identical), RN7SL220P (79% identical), RN7SL481P (79% identical), RN7SL322P (79% identical), RN7SL679P (79% identical), RN7SL296P (78% identical), and 702 more.